CD70 (CD70 molecule)
Diseases named in the same sentence as CD70 in open-access papers (continued):
Sharing a sentence is not in itself a finding about the gene and the disease.
tumor (continued). "For instance, the use of CD70-specific CAR T cells, which recognize CD70 positive GBM in vitro, promotes tumor regression in the xenograft and syngeneic GBM models." (PMID 33671796, 2021). "We also detected other epigenetically regulated genes in this signature, including CD70, IRAK, IL20RA, THBD, TACSTD2, and MST1R, with implications related to the tumor immune microenvironment." (PMID 34150764, 2021). "Indeed, CD70 expression is an independent predictor of poor OS for patients with low-grade gliomas (LGG) and GBM, correlating with chemokine-mediated immune modulation, tumor aggressiveness and immunosuppression via tumor-associated M2 macrophage recruitment/activation in GBM." (PMID 34163465, 2021). "Their respective ligands are OX40L, CD137L, CD70 and ICOSL on APCs or tumor cells and CD40L on T cells." (PMID 34439292, 2021). "Neither the number of CD8, FOXP3, nor CD27-positive TIL showed difference between CD70-high and low tumor, whereas the number of FOXP3-positive iTIL in CD70-high TSCC was slightly higher than CD70-low (p = 0.07)." (PMID 35145909, 2021). "In contrast to EpCAM, CA9, CD70, and CD147 represent promising tumor-specific biomarkers for EVs in ccRCC." (PMID 33276608, 2020). "Tumors were allowed to establish for seven days and then NSG mice were intravenously injected with NT, CD70 CAR2, B7-H3 CAR or TanCAR-T cells on day 7 post tumor inoculation." (PMID 32685008, 2020). "For analysis of anti-tumor efficacy, NCI-H460, A375, MDA-MB-435 and 786-O were served as CD70+/B7-H3+ cell lines." (PMID 32685008, 2020). "We also observed that CD70, ITGB4, and DCBLD2 were significant prognostic indicators in crosstalk and cell-cell communication between LUAD tumor cells and T cells." (PMID 32549766, 2020). "In tumor tissues, we found an increased expression of CA9, CD70, and CD147 were increased in cell lysates and EV fractions compared to normal tissues." (PMID 33276608, 2020). "EVs were characterized using transmission electron microscopy, nanoparticle tracking analysis, and Western blotting using exosome and putative tumor markers (epithelial cell adhesion molecule (EpCAM), carbonic anhydrase 9 (CA9), CD70, CD147)." (PMID 33276608, 2020). "More specifically, CD70 is confirmed to be overexpressed in recurrent tumors and tumors with MES gene signatures of GBM and accordingly plays a role in the promotion of tumor migration." (PMID 32429463, 2020). "After confirming the expression of CD19 and CD70 in his tumor samples, the patient was given lymphodepletion chemotherapy followed by infusion of 4th generation CD19-CAR T-cells (4SCART19) and 4th generation CD70-CAR T-cells (4SCART70)." (PMID 31867275, 2019). "The TNFR superfamily proteins are expressed by antigen-presenting cells (APC) or tumor cells, including TNFSF4 (OX40L), TNFRSF5 (CD40), TNFSF7 (CD70), TNFSF9 (CD137L), TNFRSF14 (HVEM), and TNFSF18 (GITRL)." (PMID 30609841, 2019). "Twenty-five MCL samples (38%) were positive for both CD70 and CD27, whereof 60% (15 samples) showed double positivity within ≥ 50% of tumour cells." (PMID 31652572, 2019). "Based on the intersection of TNF superfamily signature between human BC tissues and cell lines to exclude the tumor heterogeneity, both TNBC tissues and cell lines dominantly expressed CD70 and TNFSF9." (PMID 30728901, 2019). "It was shown that TADCs modified with CD70 and simultaneously activated via CD40 and TLR4, were able to migrate to tumor draining lymph nodes and stimulate tumor-specific CD8+ T cells." (PMID 30233579, 2018). "Hence, combining modifications of early DC activation processes, such as caTRL4, CD40L, CD70 with elimination of immunosuppressive signaling, such as IL-10R and PD-L1, may drive optimal anti-tumor T cell responses by maximizing both co-stimulatory/co-inhibitory ends of the spectrum." (PMID 29867960, 2018).
tumor (continued). "In spite of this, in most studies, biological effects of CD70 have been demonstrated to be mediated by interactions of CD70 with its receptor CD27, which can have a dual role in regulating anti-tumor adaptive immune responses." (PMID 25792975, 2015). "ARGX-110, a human CD70-specific monoclonal antibody which is currently undergoing Phase I clinical testing, is a strong antagonist of CD70/CD27 signaling and mediates destruction of CD70-expressing tumor cells through enhanced ADCC." (PMID 25951351, 2015). "We have assessed the co-expression of CD70 and CD27 in non-small cell lung cancer (NSCLC) by immunohistochemistry to explore a correlation between expression of the protein and tumor histologic subtype, genetic aberrations and prognosis." (PMID 25951351, 2015). "In this study, CD70 expression was detected both in NCSLC cells (16%) and on TILs in the tumor microenvironment (55%)." (PMID 25951351, 2015). "Our results revealed CD70 expression on the surface of both primary and metastatic NSCLC tumor cells and in the tumor microenvironment." (PMID 25951351, 2015). "Induced expression of both CD70 and CD40L by tumor cells was shown to impede tumor growth and initiate anti-tumor immunity." (PMID 23450201, 2013). "Bone marrow from WM patients contains elevated numbers of mast cells, which use CD70 (a ligand for the TNF-receptor superfamily member, CD27) on the cell surface to bind soluble CD27 (sCD27) secreted by tumor cells." (PMID 24106612, 2013). "Thus, in the tumor micro-environment CD70 may promote tumor growth and immune evasion." (PMID 23840967, 2013). "Expression of CD70 was also examined in 11 clear cell RCC (ccRCC) metastatic patient tissues, two of which had matched primary ccRCC tumour tissue for comparison." (PMID 16892042, 2006). "In total, 90 donor tumour tissues were examined; however, only RCC tissues showed strong staining with the anti-CD70 antibody, with 16 out of 30 (53%) cases showing CD70 immunoreactivity." (PMID 16892042, 2006). "They code for co-stimulatory molecules known to enhance tumor cell immunogenicity: CD80, a member of the B7 family and CD70, a member of the TNF family." (PMID 15279677, 2004). "In HNSCC, CD70 is overexpressed in certain subtypes, particularly in tumors of the larynx, oral cavity, and tongue, but not in those arising from the hard palate, hypopharynx, lip, or oropharynx." (PMID 40650111, 2025). "While multiple studies reported CD70 expression in situ on tumor cells, no other detailed break-down of the molecule’s TME protein expression pattern is currently available in the scientific literature." (PMID 40205178, 2025). "The specific roles of these CD70‐positive nontumour cells in tumour progression, metastasis, and therapeutic resistance remain poorly defined." (PMID 40629902, 2025). "Consistent with our findings, CD70 clustering can initiate reverse signaling through its cytoplasmic tail, engaging PI3K/AKT, MAPK and NF-κB pathways that promote proliferation, EMT, invasion, and immune-evasive phenotypes in tumor models." (PMID 41510255, 2025). "Furthermore, we quantified the tissue expression of CD70’s receptor, CD27 in the TME and its colocalizing expression signals with tumor- stromal and immune cells." (PMID 40205178, 2025). "Among these, CD70 was found to be highly expressed on tumor cells while being largely absent in normal tissues." (PMID 40885188, 2025). "Meanwhile, the expressions of IKZF3 and CD70 were significantly higher in tumor tissues than those in normal tissues." (PMID 40860241, 2025). "In our study, we utilized the 1% O2 condition to mimic the hypoxic environment, and observed that hypoxia severely impaired survival, proliferation, memory phenotypes, cytokine production, and anti-tumor cytotoxicity of both anti-MSLN and anti-CD70 CAR-T cells." (PMID 41199316, 2025).
tumor (continued). "The combination of restricted antigen expression demonstrated in vivo efficacy, and early clinical translation supports further development of CD70 CAR constructs, particularly those incorporating NK-optimized signaling motifs to maximize cytotoxicity while minimizing off-tumor reactivity." (PMID 41303706, 2025). "In dermal fibroblasts, TGF-β–induced CD70 enhanced NF-κB activation and secretion of IL-6 and MCP3, thereby reinforcing paracrine inflammatory loops that supported cSCC spheroid expansion and tumor progression." (PMID 41510255, 2025). "Solar UV–induced DNA damage robustly induces CD70 expression via E2F1, which in turn mediates keratinocyte and cSCC cell proliferation through MAPK and NF-κB signaling, driving the expression of inflammatory mediators and tumor-promoting factors such as IL1B." (PMID 41510255, 2025). "Remarkably, CD70-specific CAR-T cell therapy showed profound anti-tumor effects in GBM without observed toxicity." (PMID 41233805, 2025). "Conversely, aberrant expression of CD70 has been observed in several types of malignancies, such as RCC and nasopharyngeal carcinoma, leading to lymphocyte apoptosis, T cell exhaustion and immune evasion, which promote tumor progression." (PMID 41233805, 2025). "Moreover, silencing CD70 downregulated stem-related markers (CD44 and SOX-2), inhibited tumor growth and migration, promoted immune suppression by attracting monocyte-derived M2 macrophages, further highlighting its therapeutic potential." (PMID 41233805, 2025). "Ongoing phase-I trials with CGC729, an anti-CD70 CAR-NKT cell, showed preliminary evidence for tumor response in both CD70 positive and negative tumors." (PMID 40260236, 2025). "Additionally, ATRX mutations, EGFR (epidermal growth factor receptor) alterations, CD70, CD147, CDKN2A deletions, exosomes, cfDNA (cell-free DNA), ctDNA (circulating tumor DNA), and CTCs (circulating tumor cells) stand out as significant markers." (PMID 38732975, 2024). "CD70- and/or POSTN-positive CAFs may have limited capacity for the modulation of the tumor immune microenvironment." (PMID 38473788, 2024). "This interaction activates the CD27/CD70 signalling pathway, promoting effector and memory T‐cell differentiation in CD8+ T cells, thereby enhancing their functionality and active participation in the immune response against tumours." (PMID 39031800, 2024). "However, the effect of adding smKI to RT on the expression of CD70 and OX40-L exhibited strong cell line-specificity, making it difficult to predict an overall anti-tumor immune response." (PMID 39411143, 2024). "When the average tumor size was about 100 mm3, animals received a single IV dose of 2 × 107 CD70-CAR or non-transduced T cells as control." (PMID 38637886, 2024). "Upregulation in both irradiated and non-irradiated (abscopal) tumor was found when all three co-stimulatory molecules were stained together (CD70+ CD83+ CD86+ DCs)." (PMID 38646638, 2024). "Consequently, the E066 scFv was selected, leading to the construction of CD70 CAR-T cells with high specificity, strong anti-tumor efficacy, and fratricide-resistance." (PMID 39906740, 2024). "We analyzed CD70 expression across various tumor types and corresponding normal tissues using multiple online databases, including TIMER, GEPIA, GENT2, TNMPlot, and GSCA, all of which utilize data from TCGA datasets." (PMID 39446784, 2024). "In line with what is reported in literature, no other cell types, except for a few activated tumor-infiltrating lymphocytes, were found positive for CD70 in the TME." (PMID 38331849, 2024). "Importantly, we identified several lymphocyte activation ligands that were significantly upregulated on Ccr7_DC.2 versus other tumour CCR7+ DC states and Kaede-red dLN CCR7+ DCs, such as Il12b, Tnfsf4, Tnfsf9, Cd70 and Pvr." (PMID 38267413, 2024). "Unlike what is seen in CRC, where CD70+ CAFs were always found adjacent to the tumor cells, we did not detect such a pattern in PDAC." (PMID 38331849, 2024).
tumor (continued). "NSG mice were subcutaneously injected with 1.0 × 106 Raji cells mixed with Geltrex and when tumor size reached 50 mm2, mice were treated twice (three days in between) with 1.0 × 107 MOCK control NK cells, CD70-CAR NK cells, or CD70-CAR-IL-15 NK cells or left untreated." (PMID 38331849, 2024). "Interestingly, global CD70 KO significantly increased the frequency of CD19 + B cells, probably due to reduction of Treg suppression or the increased tumor burden in these mice." (PMID 39105866, 2024). "Yet, treatment with CD70-CAR NK cells did not result in a significant difference in tumor growth or survival compared to treatment with MOCK NK cells." (PMID 38331849, 2024). "Moreover, we developed dual-targeted anti-CAIX/CD70 CAR-T cells to enlarge the target cell population and mitigate tumor heterogeneity." (PMID 38195534, 2024). "Furthermore, we compared CD70 expression across different tumor types using the UALCAN database, which revealed that CD70 expression in DLBCL was higher than in most other cancers." (PMID 39446784, 2024). "All three NK cell therapies (MOCK, CD70-CAR, and CD70-CAR-IL-15) significantly delayed tumor growth over time and improved survival compared to the untreated control group (Median survival untreated: 18 days, MOCK: 21.5 days, CD70-CAR: 21.5 days, and CD70-CAR-IL-15: 27 days)." (PMID 38331849, 2024). "Finally, to investigate a potential transactivation of CAR T cells by tumor cells, we checked the expression of co-stimulatory ligands, such as CD70, 41BBL, CD80, and CD86, on BxPC-3 tumor cells by flow cytometry." (PMID 37287982, 2023). "When tumor cells overexpress CD70, CD27 expression in tumor-infiltrating Tregs may facilitate immune evasion." (PMID 37849799, 2023). "Moving one step forward, adoptively transferred CD70-expressing immature DCs could prime CD8+T-cells, by CD27, to become tumor-eradicating cytolytic effectors and memory cells with a capacity for robust secondary expansion, independently of CD4+T-helpers." (PMID 37345056, 2023). "On the other hand, in-vivo CD27 engagement by CD70 on B-cells has shown to augment primary CD8+T-cell responses and tumor rejection even in poorly immunogenic tumor models, as CD27 stimulation can boost antigen-specific CD8+T-cell expansion and concomitantly improve per-cell cytotoxic functionality." (PMID 37345056, 2023). "Further, the tumor cell surface expression of immune-activating (OX40L, CD137L, CD70, and ICOSL) and immune-suppressive (PD-L1, PD-L2, HVEM) checkpoint molecules and of an oncogenic molecule (EGFR) were measured via multicolor flow cytometry after CT and RT alone or after RCT." (PMID 36480032, 2023). "The lysis EC50 for IMM40H was 0.395 nM in Raji cells, whereas IMM40H had no CDC activity against other CD70+ tumor cell lines, including U266B1, Daudi, Jeko-1, and A498 (data not presented)." (PMID 37849799, 2023). "Furthermore, relative to CD19-CAR-T cells and control T cells treatment, CD70-CAR-T cells significantly prolonged the survival of mice bearing AML cells and effectively inhibited tumor growth." (PMID 36845088, 2023). "PDT with the construct resulted in significant tumor growth inhibition as well as increased expression of CD70 and CD40 in CD11c+ DCs in tumor-draining lymph nodes and enhanced IFN-y levels in serum, suggesting that the treatment induces an antitumor immune response." (PMID 36839652, 2023). "The tumor-to-blood and tumor-to-muscle ratios of [68Ga]Ga-NOTA-anti-CD70 VHH in CD70high tumors were 9.99 ± 2.83 and 18.93 ± 7.85, respectively, and were significantly higher than those in CD70low tumors (T/B: 1.84 ± 0.06; p = 0.0076, and T/M: 3.02 ± 1.10; p = 0.0254)." (PMID 37093350, 2023). "Preliminary in vitro analysis has indicated that blocking CD70 or CD27 can mitigate Raji-specific T-cell activation, however, in vivo data with CD70 KO Raji cells indicated that T-cell-mediated tumor control is not solely dependent on the CD70-CD27 axis." (PMID 37087494, 2023).
tumor (continued). "Similarly, greater downregulation of tumor promotion proteins such as CCL17, CD70, and LAMP3 during dual therapy suggests that dual therapy further augments tumor suppression." (PMID 36572780, 2022). "The CD70 locus was indeed identified as a direct target of SOX11, and could be induced thanks to CD40-L stimulation, part of the tumor B/TME interaction." (PMID 35804999, 2022). "Finally, a PD‐1–CD70 fusion protein has recently been described that can target tumour cells by blocking the PD‐1–PDL1 interaction and provide the missing CD70 activation signal to CD27+ T cells." (PMID 36471481, 2022). "CD27/CD70 interaction normally boosts T cell activation, differentiation, and promotes the clonal expansion of effector T cells, features for which CD27 targeting is being exploited in antibody-mediated anti-tumor strategies." (PMID 35053463, 2022). "In addition, cytotoxicity enhanced the expression of the T-cell costimulatory ligands CD70, CD80, and CD86 while stimulating tumor infiltration of APCs, thus improving the antitumor effects." (PMID 36185263, 2022). "When CAR T cells were generated to target cancer cells that express CD70, HNSCC expressing CD70 were efficiently killed and CD70 negative tumor cells were not targeted." (PMID 36338731, 2022). "In most human tumours, FAM46C was negatively correlated with CD70." (PMID 35222533, 2022). "Both the ligand, CD70, and its receptor, CD27, are independently expressed in tumor tissue." (PMID 36180422, 2022). "sCD27 might interfere with the conjugation of membrane-bound CD27 and CD70, thereby affecting the priming of CD8+ T cells and subsequent anti-tumor immunity." (PMID 35874720, 2022). "The injection of naked TriMix mRNA (caTLR4 and co-stimulatory ligands CD70 and CD40L; ) directly into the tumor resulted in systemic therapeutic anti-tumor activity in various mouse models and led to a phase I clinical trial in patients with early, resectable breast cancer lesions (NCT03788083)." (PMID 33858437, 2021). "To maintain a bivalent interaction with the tumor antigen of choice, we chose to replace the C-terminal scFv antibody in homodimeric tetravalent BiMAb by the ectodomain of either 4-1BBL, OX40L, TL1A or CD70." (PMID 34484225, 2021). "Delivery of CD70 mRNA only marginally affected tumor growth in both the treated and non-treated tumor." (PMID 33658037, 2021). "Although the sample size was small, these results may imply that adding CD70 to the IHC panel has a potential to improve the specificity and sensitivity of TSCC diagnosis, especially when biopsy is the only source of tumor tissue." (PMID 35145909, 2021). "In the NPC microenvironment, CD70 is highly and specifically expressed on tumor cells rather than T cells and dendritic cells (DCs)." (PMID 34568077, 2021). "Examined by immunofluorescence using purified human B7-H3 scFv-mFc and CD70 scFv-mFc fusion protein as primary antibody, expression of CD70 and B7-H3 could be detected on the surface of NCI-H460, A375, MDA-MB-435 and 786-O tumor cells." (PMID 32685008, 2020). "In contrast to EpCAM, CA9, CD70, and CD147 could represent promising markers to identify tumor-specific EVs in ccRCC." (PMID 33276608, 2020). "Therefore, we selected carbonic anhydrase 9 (CA9), CD70, and CD147 as highly promising tumor specific markers on exosomes in RCC, since they have been shown to be upregulated during tumor development and progression in clear cell RCC." (PMID 33276608, 2020). "CD70 and CD27 expression was demonstrated in a broad range of tumour types." (PMID 31652572, 2019). "We reported that CD70 tumor expression is an independent indicator of poor survival for patients with lower-grade gliomas (LGG) and GBM, correlating with chemokine-mediated immune inhibition, tumor erosion, proliferation, and migration in GBM24." (PMID 31488817, 2019).